ENSG00000201827
Gene: Small nucleolar RNA gene on chromosome 3 (133,551,186 to 133,551,315, forward strand). Ensembl gene ENSG00000201827.
Homologues: Orthologues: rat LOC120098367 (52% identical), rat Snora33 (52% identical), mouse Snora33 (48% identical), mouse Gm23722 (42% identical), mouse Gm55990 (38% identical). Paralogues in human: SNORA33 (53% identical).